MYD88 (MYD88 innate immune signal transduction adaptor)
Diseases named in the same sentence as MYD88 in open-access papers (continued):
Sharing a sentence is not in itself a finding about the gene and the disease.
Sepsis (continued). "Thus, developing methods of suppressing the uncontrollable activation of TLR/MyD88 signaling may prevent host-mediated damage of patients with sepsis." (PMID 34557182, 2021). "Therefore, luteolin could counteract sepsis inflammation by inhibiting the PPAR-γ/STAT/MyD88 pathway." (PMID 34594472, 2021). "However, the data support that endothelial MyD88 is not required for loss of BBB integrity during CLP sepsis." (PMID 26790027, 2016). "Moreover, myd88-deficient mice are highly susceptible to polymicrobial sepsis because the lack of the adaptor protein involved in most of TLR signaling prevents the establishment of the local inflammatory response." (PMID 27199981, 2016). "Supporting the hypothesized role of TLR9 pathway in sepsis, our results showed an increase in myocardial expression of MYD88 and RAGE, both of which function as downstream TLR9 factors, as well as a formation of physical interaction between RAGE and its ligand TFAM." (PMID 26448624, 2015). "As expected, MyD88-deficient mice were more susceptible to non-severe and moderate sepsis." (PMID 25084278, 2014). "Additionally, we addressed the role of MyD88 in the onset of sepsis." (PMID 25084278, 2014). "Moreover, although MyD88 is also downstream of the IL-1R and IL-18 pathways, neutrophil recruitment 6 h after non-severe sepsis induction was similar between IL-18-deficient mice treated with IL-1Ra and control mice." (PMID 25084278, 2014). "By creating chimeric mice using bone marrow (BM) transplantation, we reported the importance of MyD88 in both radiosensitive (hematopoietic) cells and radioresistant (parenchymal) cells for antibacterial defense and survival during Klebsiella pneumonia derived sepsis." (PMID 25254554, 2014). "Hence, although MyD88 may contribute to organ injury during sepsis, its role likely depends on the type and primary source of the infection." (PMID 25254554, 2014). "Furthermore, in a model of sepsis caused by polymicrobial infection both systemic and hepatic inflammatory responses were strongly attenuated in the absence of MyD88." (PMID 18946505, 2008). "The expression of PD-1; PD-L1; TLR-5, -6, and -9; MYD88; IRAK1; TIRAP; and NFkB was quantified by RT-PCR at 24, 48, and 72 h after CLP-induced sepsis." (PMID 40076895, 2025). "During sepsis, cfDNA primarily triggers inflammatory responses by activating specific PRR pathways, including TLR9-myeloid differentiation primary response 88 (MyD88), AIM2 inflammasome, and cGAS-STING pathways." (PMID 41327452, 2025). "In sepsis, lipopolysaccharide (LPS) activates selective autophagy through TLR4-MyD88-dependent or MyD88-independent as well as NF-kB pathways." (PMID 40364841, 2025). "Furthermore, Sj-Cys also mitigated sepsis-induced cardiomyopathy by inhibiting the lipopolysaccharides (LPS)-myeloid differentiation primary response 88 (MYD88) inflammatory signaling pathway and might have some therapeutic efficacy in the sepsis-associated cardiac dysfunction." (PMID 39314046, 2024). "As the liver is one of the key target organs during sepsis, the proteins of TLR4, myD88, and NF‐κB in the livers were assayed to clarify the role of this pathway in the LPS‐induced sepsis." (PMID 38455195, 2023). "Key findings: MAF reduces LPS‐induced inflammatory reaction in vitro and in vivo; MAF exerts its anti‐inflammatory effect by inhibiting the TLR4/MyD88/NF‐κB pathway; MAF corrects intestinal flora imbalance during early stage of sepsis to some degree." (PMID 38455195, 2023). "It has also been recognized that circANKR inhibits the NF-κB signaling pathway by acting on the miR-31/MyD88 axis, and lncRNA TUG1 also alleviates sepsis-induced acute lung injury by targeting miRNA-34b-5p." (PMID 36526959, 2022). "Reinforcing this observation, genes involved in the MAPK, mTOR, TLR2/MyD88 and JAK/STAT pathway are also up-regulated in the LPS group, as recently described in sepsis patients, confirming the pertinence of such approaches." (PMID 35742875, 2022).
Sepsis (continued). "The NF-κB signaling pathway is one of the key regulatory pathways of inflammatory response, and the changes in the expression of pathway-related genes such as CD14, MyD88, TNF-α, IL-1β, and IL-1R play an important role in the development of sepsis." (PMID 35186224, 2022). "In our study, phosphorylation of NF-κB and levels of TLR4 and MyD88 proteins in the model group increased after LPS stimulation, but these factors were significantly inhibited by EA at ST36 in the alleviation of sepsis." (PMID 35722155, 2022). "EA at ST36 prevented sepsis from worsening by inhibiting inflammation and apoptosis, which correlated with the regulation of the TLR4/NF-κB/MyD88 signaling axis and modulation of the intestinal flora." (PMID 35722155, 2022). "The migration of neutrophils to the kidney during sepsis is dependent on the activation of TLR2, TLR4 and the adapter molecule-MyD88." (PMID 36010680, 2022). "In this study we have presented results demonstrating that Ts-AES strongly alleviate excessive inflammation via stimulating Tregs response and inhibiting the HMGB1/TLR2/MyD88 signal pathway, and protect mice from ALI induced by sepsis." (PMID 33842398, 2021). "It is thus plausible that the TLR4/MyD88/PLD1 axis mediates increases in PA pools that serve as substrates for lipin-1 during the events of macrophage proinflamatory activation and sepsis development described in this study." (PMID 34757442, 2021). "The HMGB-1, MyD88, TLR4, and NF-κB mRNA expressions were upregulated in the sepsis groups than in the NC group." (PMID 33859538, 2021). "Innate stimulants such as beta-glucan can generate immune-enhancing trained immunity through MyD88 and/or TRIF dependent activation of PI3K pathway, and exert protective effects in experimental sepsis." (PMID 34777396, 2021). "ROC analysis revealed circulatory levels of MYD88 and NFKB1 transcripts to be good biomarkers for sepsis in neonates." (PMID 34183713, 2021). "Across all neonates, relative expression levels of MYD88 (p < 0.001), NFKB1 (p < 0.001), and IL6 (p = 0.027) were significantly higher in sepsis cases compared to controls." (PMID 34183713, 2021). "When released secondarily during a primary acute inflammatory process like sepsis and infection or autoimmune and autoinflammatory reactions, S100A8/A9 amplifies the primary pro-inflammatory response by activating the MyD88-dependent TLR4 signaling pathway." (PMID 32425933, 2020). "NF-κB upstream targets genes, MCP-1, IL-1R, and MyD88, which were significantly upregulated in CLP-induced sepsis mice, were attenuated by Decitabine treatment." (PMID 32714333, 2020). "The DE miRNAs (miR-1246, miR-200, miR-223, miR-29b, and miR-145) reported earlier in sepsis patients, for example, contribute to regulation of signaling molecules (IKKα, MAL, TRAF6, MyD88) in the TLR-4 pathway during LPS exposure." (PMID 33113825, 2020). "Our research team has shown that corilagin exerts an anti-inflammatory effect in sepsis through downregulation of expression of TLR4, MyD88, TRIF, and TRAF6 in the TLR4 signaling pathway." (PMID 32849545, 2020). "Here we show that in a mouse model of acute sepsis, bacterial lipopolysaccharides (LPS) suppress medullary erythroblastic islands (EBIs) and erythropoiesis in a TLR-4- and MyD88-dependent manner with concomitant mobilization of HSCs." (PMID 33123170, 2020). "The major adapter for TLR signals, MyD88, has been shown to be required for MDSC accumulation in a model of sepsis." (PMID 31849990, 2019). "Similar to the findings at 48 hpi, the majority of both WT and Myd88−/− mice had very high levels of IL-6, TNF-α, and IL-10, indicative of progressing sepsis." (PMID 30642901, 2019). "Flow cytometry analysis further revealed that downstream effectors of TLR9, including IRF3, MyD88, and TRAF3, were elevated in all of the sepsis patients compared with the normal donors, and was correlated with improved prognosis in patients with sepsis." (PMID 31534550, 2019).
Sepsis (continued). "In sepsis, TLR4 independent and myeloid differentiation primary response protein 88 (MyD88) dependent activation controls MDSC functions." (PMID 30405617, 2018). "As an important molecule of acquired immune, TLR4 activates mononuclear phagocyte system, leading to a cascade of inflammation through MyD88 and TRIF pathways resulting in SIRS and sepsis eventually." (PMID 28056977, 2017). "Moreover, it has been reported that histones and myeloperoxidase could be responsible for NET-induced endothelial dysfunction, and histones can also interact with TLR2 and TLR4 to induce cytokine production via MyD88 signaling, contributing to the systemic inflammatory response observed in sepsis." (PMID 27199981, 2016). "Compared with sham group, CLP-induced sepsis dramatically increased TLR4 and MyD88 mRNA expression in both CLP and yohimibine groups (P < 0.01)." (PMID 25929655, 2015). "In summary, this study demonstrated that CLP-induced sepsis promoted the expression of TLR4 and Myd88 and the activation of ERK1/2 and NF-κB in lung tissue, and ultimately induced the generation of TNF-α and IL-6 in BALF and plasma." (PMID 25929655, 2015). "Both Mito-Vit-E and TLR9 inhibitor OND-I repressed LPS-induced up-regulation of MYD88, RAGE, ASC, activated caspase 1 and IL–1β, confirming that sepsis induces a mtROS dependent mtDNA-TLR9 pathway in cardiomyocytes." (PMID 26448624, 2015). "MyD88 is a key protein in the signaling pathway initiated by TLR, which can be of significant importance during sepsis." (PMID 25054155, 2014). "We previously showed that ALI secondary to sepsis was milder in alloxan-induced diabetic rats and involved the adaptor molecule of the IL-1 receptor family (which includes TLR-4), MyD88." (PMID 25398720, 2014). "In kidney tissue after sepsis, TLR2 and TLR4 mRNA is highly expressed in the WT mice, which also have a six-fold increased expression of MyD88." (PMID 22655058, 2012). "We concluded that the migration of neutrophils to the kidney after sepsis is dependent on the activation of TLR and MyD88 and mostly decreases the release of pro-inflammatory cytokines." (PMID 22655058, 2012). "The expression of MyD88 is inhibited by SOCS-1 and we observed that, in our sepsis-induced ALI model, the alveolar macrophages from diabetic animals over-expressed SOCS-1 mRNA." (PMID 23024779, 2012). "Feng and colleagues compared the different role of MyD88- and Trif-signaling in endotoxemic and CLP models of sepsis." (PMID 21977329, 2011). "In LPS-induced sepsis rat model, PF pretreatment inhibited PI3K/Akt/ERK-mediated HIF-1α and TLR4/MyD88/NF-κB signaling, thereby reducing inflammation by decreasing the levels of tumor necrosis factor-α (TNF-α) and interleukin-1β (IL-1β) in serum and cardiac tissue." (PMID 41311552, 2025). "PCR analysis revealed the significant up-regulation of MyD88 and TIRAP during sepsis." (PMID 40076895, 2025). "To test this, we immunized mice lacking MyD88 and tested survival in our polymicrobial sepsis model." (PMID 41170853, 2025). "In a cecal ligation and puncture (CLP)-induced sepsis rat model, calycosin treatment was shown to decrease the levels of HMGB1, MyD88, p-NF-κB, and NLRP3, as well as the contents of pro-inflammatory cytokines such as TNF-α and IL-1β, at the significantly effective dose of 50 mg/kg." (PMID 41463300, 2025). "Additionally, TsAg conferred a therapeutic effect on sepsis-induced acute lung injury through activating Tregs and inhibiting pro-inflammatory cytokinesvia the high mobility group box 1/TLR2/MYD88 signaling pathway." (PMID 39314046, 2024). "During physical exercise, muscle and adipose tissue produce a substance called irisin, which decreases the expression levels of TLR3, TLR4, MyD88, MAPK, and NF-kB, thereby reducing the release of pro-inflammatory factors and preventing the development of sepsis." (PMID 38049851, 2023).
Sepsis (continued). "In C4_RPL34 cells in the context of S. viridans sepsis, genes co-expressed with CTSD were related to “Leukocyte migration,” “Intrinsic apoptotic regulation,” and “MYD88: MAL cascade initiation,” which may contribute to disease pathogenesis." (PMID 37919720, 2023). "The results indicated that the anti-inflammatory effect of EgCF on serious bacterial infections such as sepsis may take place through inhibition of the TLR2 and MyD88 inflammatory signaling pathway." (PMID 38066526, 2023). "It activates MyD88 then NF‐κB and finally releases inflammatory cytokines including TNF‐α, interleukin‐1β (IL‐1β), and IL‐6 which play crucial roles in occurrence and development of sepsis." (PMID 38455195, 2023). "Then, we developed a prognostic risk score with six pyroptosis-related genes, including GZMB, CHMP7, NLRP1, MYD88, ELANE, and AIM2, and found that it could predict the prognosis of sepsis patients." (PMID 36618365, 2022). "Our results suggest that alleviation of sepsis may correlate with the downregulation of levels of TLR4, NF-κB, and MyD88." (PMID 35722155, 2022). "MYD88, NFKB1, and IL6 relative expressions were significantly higher in sepsis cases than controls." (PMID 34183713, 2021). "ROC analysis revealed MYD88 and NFKB1 transcripts to be good biomarkers for sepsis." (PMID 34183713, 2021). "Both the in vivo and the in vitro data suggest that the GSS has anti‐apoptotic effects on LPS‐induced lung vascular EC injury via TLR4/ Myd88/NF‐κB/BCL‐2 signalling, which may be the main reason why GSS effectively alleviates sepsis‐induced ALI." (PMID 31756053, 2020). "While these results provide testament for the therapeutic potential of RSV against systemic inflammatory response (such as sepsis), the direct link between RSV-induced autophagy and its potential involvement in the degradation of MyD88 is worthy of further investigations." (PMID 33139717, 2020). "Myeloid differentiation primary-response gene 88 (MyD88), an important cytoplasmic adaptor molecule for integrating and transducing the signals triggered by all Toll-like receptors (TLRs) family except TLR3, has been reported inducing MDSC expansion in sepsis." (PMID 32641056, 2020). "rSj-Cys at dose of 10 μg had the better inhibitory effects on the expression of MyD88 than the doses of 50 μg compared to mice with sepsis without treatment in liver and in lung." (PMID 28482922, 2017). "The rise in the number of CD11chiCD4+ pDCs in the bone marrow during sepsis was dependent on signaling through MyD88, but not on TLR4." (PMID 29218051, 2017). "Expression levels of Selp, Ccl2 and Il1r1 were robustly increased by CLP sepsis irrespective of genotype, suggesting that endothelial MyD88 is not required for transcriptional responses to CLP in hippocampal vasculature, microglia and neurons." (PMID 26790027, 2016). "MyD88 is responsible for most canonical TLR signaling, such as TLR4-mediated sensing of LPS, as well as for canonical IL-1 signaling, and is thus broadly required for multiple cellular responses during polymicrobial sepsis." (PMID 26790027, 2016). "Here, we demonstrate that blood-brain barrier permeabilization and hippocampal transcriptional responses during polymicrobial sepsis occur even in the absence of MyD88-dependent signaling in cerebrovascular endothelial cells." (PMID 26790027, 2016). "In order to distinguish between these two models, we employed a powerful imaging method, transcranial two-photon imaging, the results suggesting that endothelial MyD88 is not required for BBB deterioration during sepsis." (PMID 26790027, 2016). "Contrary to TLR2- or TLR4-deficient mice, mice which are deficient in Myd88, a signalling module shared by many TLR receptors, failed to deal with mild or moderate sepsis and succumbed rapidly to infection." (PMID 26147469, 2015).
Sepsis (continued). "Innate immunity participates in polymicrobial sepsis-induced AKI, mainly through the MyD88 pathway, by leading to an increased migration of neutrophils to the kidney, increased production of proinflammatory cytokines, vascular permeability, hypoxia and apoptosis of tubular cells." (PMID 22655058, 2012). "Targeting the Myd88 pathway using a peptide loaded into EVs (EVMyd88), had been described to be efficient in a model of sepsis, although in that study non-targeting but anti-inflammatory Mesenchymal Stem Cell vesicles were used, which enhanced peptide functionality in vitro." (PMID 39885580, 2025). "To investigate the expression patterns of Cbl and MyD88 in clinical samples, we analyzed the transcriptional profiles of blood samples from three GSE datasets and found that Cbl, along with elevated MyD88 expression, was upregulated in both sepsis patients and pneumonia patients." (PMID 41562051, 2025). "Thus, activated brain pericytes may play a role in the initial inflammatory response during sepsis through the release of cytokines and chemokines mediated by LPS-induced TLR4/Myd88 signaling, with Fli-1 acting as a crucial regulator in this process." (PMID 39862276, 2025). "Combined with the results of in vitro studies on macrophages, the potential mechanism by which rEgAgB ameliorates sepsis-induced hyperinflammatory response may be to shift the M1-like to M2-like phenotype of macrophages through inhibiting TLR2 and MyD88 pathways." (PMID 39548530, 2024). "We infer that the down-regulation of MyD88-signaling, as marked on target TPKO signaling pathways, should significantly diminish proinflammatory responses by eliminating the downstream “cytokine storm”, similar to the scenario we previously discussed in infectious CASP-model sepsis." (PMID 37033947, 2023). "In our study, Corilagin showed capability of inhibiting the expression of TLR4 signaling molecules in both MyD88 and TRIF signaling pathways, which demonstrated that Corilagin might be a potential agent to rescue the patients from extreme inflammatory status in sepsis." (PMID 28056977, 2017). "Transcriptional activation in the forebrain in sepsis may be mediated by MyD88-independent endothelial mechanisms or by non-vagal neuronal pathways." (PMID 26790027, 2016). "In order to determine whether endothelial MyD88 is required for CNS transcriptional responses to sepsis, we assessed the mRNA transcript levels of a panel of genes reported to be highly expressed during CLP sepsis." (PMID 26790027, 2016). "It is perhaps not surprising that CLP sepsis could mediate conserved physiological responses through both MyD88-dependent and–independent mechanisms." (PMID 26790027, 2016). "By contrast, the adaptor protein MyD88, which is required for TLR activation, is crucial for the establishment of a local chemotactic response and neutrophil recruitment to the site of infection, which consequently determines the outcome of polymicrobial sepsis." (PMID 25084278, 2014). "Furthermore, the deleterious effect of the absence of MyD88 was also observed in mice under severe sepsis." (PMID 25084278, 2014). "Despite the reduction in the neutrophil recruitment in MyD88-deficient mice 6 h after severe sepsis induction was not significant, these mice showed diminished CXCL2 levels at the infection site under this severity of sepsis." (PMID 25084278, 2014). "Therefore, we detected the expression of MyD88 in the liver, kidney and lung tissues of mice with sepsis treated with or without rSj-Cys to investigate whether rSj-Cys protect major organ with sepsis through inhibiting MyD88 expression." (PMID 28482922, 2017). "Meanwhile, dexmedetomidine also inhibited the expression of TLR4 and MyD88 and the activation of ERK1/2 and NF-κB in the lung tissues of CLP-induced septic rats, indicating that the anti-inflammation effect of dexmedetomidine in sepsis maybe base on TLR4/MyD88/ERK1/2/NF-κB signal pathway." (PMID 25929655, 2015).